IGF1 (insulin like growth factor 1)
Diseases named in the same sentence as IGF1 in open-access papers (continued):
Sharing a sentence is not in itself a finding about the gene and the disease.
tumor (continued). "Also, it seems proteins from animal sources throughout increased insulin-like growth factor-1, and the expression of Ras homologous gene family member A and vascular endothelial growth factor receptor-2 lead to tumor progression." (PMID 38360741, 2024). "The discrepancy between circulating IGF-1 levels and those in the tumor microenvironment may be explained by the distinct autocrine/paracrine and endocrine influences of IGF-1." (PMID 38396692, 2024). "This signalling pathway influences the sensitivity of cancerous tumours to insulin and IGF1." (PMID 39001340, 2024). "IGF1 is an insulin-like growth factor, which can promote scar formation and wound healing, regulate cell proliferation and metabolism, promote tumor cell growth, inhibit tumor cell apoptosis, and promote tumor occurrence and development." (PMID 38533261, 2024). "IGF-1 induces and activates the Ras/Raf/MAPK and PI3K/Akt/mTOR pathways, thereby reducing apoptosis, promoting cell proliferation and survival, and elevating the risk of tumor development." (PMID 39432545, 2024). "By using recombinant IGFBPs tumor-promoting effects of IGF-1 signaling can be diminished." (PMID 39273251, 2024). "In addition, raised plasma insulin levels and insulin-like growth factor-1, both known to promote tumor growth." (PMID 37468880, 2023). "Differences in study subjects or the duration of follow-up between studies may explain the inconsistency in the relationship between tumor grade and IGF-1 level." (PMID 36831629, 2023). "There are also indirect antiproliferative effects; through the inhibition of circulating growth factors (e.g. insulin-like growth factor 1 and vascular endothelial growth factor) and through the inhibition of tumour angiogenesis by altering the release of nitric oxide." (PMID 37434648, 2023). "Similar to LDL cholesterol add-back, administering recombinant insulin, IGF1 and leptin to Capan-1 xenograft-bearing mice abolished fasting-induced enhancement of terbinafine activity and it also restored cholesterol content in the tumours." (PMID 37907500, 2023). "Younger age, higher preoperative GH and- or IGF-1 levels, group 2b of the clinicopathological classification, Knosp’s grade IV, MRI, T2-weighted tumor hyperintensity and sparsely granulated cytokeratin expression patterns are related to worse postoperative outcomes." (PMID 37371013, 2023). "The indirect effect of SST may be due to the inhibition of the growth factors such as IGF-1 gene expression, which indirectly inhibits the levels of IGF-1 overexpressed during tumour development." (PMID 38203605, 2023). "Clinically, IGF1 expression is associated with tumor differentiation grade, tumor invasion, and TNM stages in GC, indicating IGF1 pathway may be a promising therapeutic target for GC." (PMID 36774408, 2023). "Another study showed that recombinant human visfatin, when administered at a concentration of 10 ng/mL, significantly increased progesterone and estradiol secretion induced by IGF-1 in primary human granulosa cells and human ovarian granulosa-like tumor cell line (KGN) cells." (PMID 37889693, 2023). "Furthermore, SCFAs cause tumor growth by activating mitogen-activated protein kinase and PI3K (phosphatidylinositol-3-kinases) signaling by increasing somatomedin C (IGF-1) levels." (PMID 36845103, 2023). "PR tumor tissues showed increased IGF1 expression compared with PS tumor tissues." (PMID 37361693, 2023). "Klotho inhibits IGF-1-mediated signaling pathways, which suppress various tumor types." (PMID 37425590, 2023). "While the specific role of ATF3 (activating transcription factor 3) in the suppression of PCa with PTEN (phosphatase and tensin homolog) dysfunction is meanwhile well known, the tumor suppressor function of IGF1, CXCL10, HIF1A, CXCL8, and CSF1 in prostate carcinogenesis remains to be elucidated." (PMID 36321189, 2023). "In aggregate, these data emphasize the important role of the insulin/IGF-1 axis in tumor biology." (PMID 37509120, 2023).
tumor (continued). "Multiple predictive variables (age, gender, preoperative GH and IGF-1 levels, maximal tumor diameter, Hardy’s and Knosp’s grade, MRI T2-weighted tumor intensity, cytokeratin expression pattern, and clinicopathological classification) are related to postoperative outcomes." (PMID 37371013, 2023). "In addition to Hif1a and Vegfa upregulation, MDM-B showed differential expression of Mmp12, Mmp14, and Igf1, which were also part of the tumor microenvironment pathway." (PMID 37858232, 2023). "Insulin can also stimulate the production of IGF-1, which promotes tumor growth." (PMID 37215444, 2023). "IGF1 signaling is a proliferation signal that counts for the survival of tumor cells." (PMID 36774408, 2023). "Consequently, evidence implicated the IGF1R and its ligands, IGF1, and IGF2, in tumor development and progression including CRC." (PMID 37284192, 2023). "Furthermore, paracrine Hh ligands also promotes CAFs to produce factors, such as IGF-1, activin, lactate, which in turn fuel malignant phenotype of tumor cells." (PMID 37213270, 2023). "Finally, to strengthen relevance of these findings, we tested also combinations on MM cells co-incubated with cytokines mixtures (IL-6 and IGF-1) mimicking bone-marrow milieu: anti-tumor activity was kept also in this context." (PMID 36830052, 2023). "Epidemiological study indicates a link between blood IGF-1 levels and the incidence of prostate, breast, and colon cancers, raising questions about the safety of long-term GH replacement in the event of de novo neoplasia, tumor regrowth, or tumor recurrence." (PMID 36675591, 2023). "Limiting glucose availability for tumours by adapting into ketosis may therefore create a metabolically unfavourable environment for tumour growth, whilst also reducing insulin and IGF-1′s growth and division stimulating signals." (PMID 37958602, 2023). "Moreover, our study showed that in all the tumor-bearing mice, there was a significant reduction in the IGF-1 levels in the groups treated with IF and combination therapy (p-value < 0.05)." (PMID 38202341, 2023). "Furthermore, our gain and loss of functional experiments showed that a PTEN/IRS1 axis is essential for the NEDD4-targeted inhibitory effect on tumor growth in IGF1 signaling-driven GC." (PMID 36774408, 2023). "Furthermore, our finding that the proportion of tumor cells expressing IGF-1 was also increased in one of two plasma cell-like clusters post-vaccine suggests that clonal selection of IGF signaling-dependent tumor clones cannot be excluded." (PMID 37790486, 2023). "Elevated insulin levels may encourage cell growth and division while affecting estrogen synthesis, metabolism, and signaling pathways, with increasing IGF-1 levels, which promote tumor growth and dissemination." (PMID 37957709, 2023). "Importantly, tumours displaying upregulation of activin responsive genes were also enriched for factors that promote SSC self-renewal, including Gdnf, Igf1, and Fgf2, indicating the tumours generate a supportive microenvironment for SSCs." (PMID 37564373, 2023). "Neutrophils can have pro- or anti-tumor effects, depending on differentiation or polarization states (i.e., N1 and N2), which are regulated by the tumor microenvironment and specifically TGFβ and IGF-1." (PMID 37371127, 2023). "Their results suggest that IGF1 through IGF1R may be involved in early stages of tumour establishment, contributing to tumour cells anchorage by interaction with soluble and non-soluble factors produced by CAFs." (PMID 37033265, 2023). "Tumor-associated fibroblasts in growing metastatic tumors have different gene expression profiles than primary tumor-associated fibroblasts or normal breast fibroblasts, and in particular, have higher levels of IGF-1 to drive tumor growth and suppress T-cell proliferation." (PMID 37046676, 2023). "Especially in cases of tumor growth there is an urgent need to control the GH/IGF1 axis." (PMID 35966052, 2022).
tumor (continued). "Thus, patients with GH ≤6 ng/ml were 21.3 times more likely to respond to SRL than those with GH >6 ng/ml, adjusted by (basal ULN_IGF-1, gender, maximum tumor diameter, and BMI)." (PMID 36187107, 2022). "sKl levels positively related to GH, IGF-1 levels and tumor volume." (PMID 36042253, 2022). "Insulin and bioavailable IGF-1 act as promoters of cell growth, angiogenesis, and lymphangiogenesis and as suppressors of apoptotic activity, mechanisms that are all considered to promote tumor development." (PMID 36262532, 2022). "The patient didn’t present any acromegalic features, IGF1 concentration didn’t correlate with tumor size, GH values were suppressed in 3 h oral glucose tolerance test and magnetic resonance imaging revealed only a cystic lesion instead of hypophyseal adenoma or hyperplasia." (PMID 35696052, 2022). "IGF-1 has been shown to promote lung fibroblast activation and collagen synthesis, and therefore may play a similar role in the tumor microenvironment." (PMID 36530465, 2022). "Indeed, KRAS mutated tumor cells induced stromal cells to secrete IGF1 and GAS6 that in turn activated IGF1R and AXL signaling in tumor cells, leading to increased mitochondrial performance, proliferative capacity, and resistance to apoptotic stimuli." (PMID 36324182, 2022). "For example, the secretion of growth factors and cytokines by astrocytes can stimulate tumor cell growth, including astrocyte-derived interleukin 6 (IL-6), transforming growth factor-beta (TGFβ) and insulin-like growth factor 1 (IFG-1) which have been shown to increase tumor cell proliferation." (PMID 36230886, 2022). "Further, they reduce the insulin and IGF-1 secretions, which are involved in tumor growth." (PMID 36139562, 2022). "Interestingly, effects of IGF1 are more pronounced, when culturing tumor cells with higher extracellular glucose levels." (PMID 35574343, 2022). "These GHA mice, with elevated GH and suppressed IGF1 in the serum, presented a significant >50% downregulation in the growth of the tumor inoculum over 3-weeks compared to the same in WT mice, as shown by Luciferin levels and caliper-based assessment of tumor volumes." (PMID 35865483, 2022). "Aside from suppressing tumor growth, IGF-1 acted on cell adhesion and motility as well." (PMID 35053528, 2022). "Since adhesion and chemotaxis were more strongly influenced by IGF-1 than was tumor cell growth, the action of IGF-1 on integrin subtype expression might be particularly important in forcing metastatic progression." (PMID 35053528, 2022). "Insulin-like growth factor (IGF-1) is associated with several oncogenic processes in cells and the IGF-1 receptor (IGF-1R) is a pivotal receptor tyrosine kinase that regulates malignant tumor transformation of ES cells." (PMID 35454895, 2022). "We may even hypothesize, that underweight and feeding problems serve as a protective mechanism to prevent further increase of the level of IGF-1 and may influence subsequent tumor growth." (PMID 35464054, 2022). "In breast tissue, IGF-1 might operate as a paracrine signal, being produced in the stromal cells but promoting tumour growth in the epithelium as demonstrated in ex vivo models." (PMID 36038791, 2022). "Since FBS may influence tumor cell growth and mask IGF-1 specific effects, tumor cell growth activity was evaluated in both an FBS-containing and FBS-free culture system." (PMID 35053528, 2022). "Therefore, the hypothalamo-hypophyseal-adrenal axis, recently described in the context of tumor-induced cachexia, is an example of the duality of the exercise-induced systemic changes in patients through the IGF1 and corticosteroids release." (PMID 36358820, 2022). "Additionally, IGF1 induces the tumor’s metastatic spread, possibly by relocating the integrins to the verge of migrating cells and via lamellipodial extension, as expressed in neuroblastoma cells." (PMID 36295107, 2022).
tumor (continued). "Besides, insulin-like growth factor-1 (IGF1) is involved in tumor overexpression of Kv10.1, an effect mediated by the Akt-dependent pathway." (PMID 35955591, 2022). "Besides, IGF-1 can facilitate tumor angiogenesis by upregulating the expression of vascular endothelial growth factor (VEGF), thereby contributing to the growth and metastases of colorectal tumor." (PMID 35296101, 2022). "Interestingly, pro-inflammatory cytokines induce tumor granule neuron precursors differentiating into astrocytes, and then astrocyte-mediated IL-4 stimulates GAMs to produce insulin-like growth factor 1, thereby further promoting tumor progression." (PMID 35572545, 2022). "Enhanced integrin α2 and β1 expression, induced by IGF1 (p-values ** 0.0040, ** 0.0028, respectively), was prevented by pre-treating the tumor cells with the specific AKT inhibitor MK-2206 (p-values ** 0.0029, * 0.0379,** 0.0035, * 0.0360, * 0.0414, ** 0.0012, respectively)." (PMID 35626034, 2022). "The insulin-like growth factors (IGFs), IGF-1 and IGF-II, which bind to the IGF receptor type 1 (IGF-1R) and the insulin receptor (IR), have been implicated in the growth, survival, and metastasis of tumor cells." (PMID 35399718, 2022). "In addition, IGF-1 appears to play a role in tumour initiation and development in insulin-resistant patients." (PMID 36290362, 2022). "In primary tumors, a high level of IGF-1 in the environment can promote tumor cell metastasis to bone, suggesting that BC bone metastasis may be IGF-dependent." (PMID 35372035, 2022). "Specifically, ACRODAT® uses the 5 key parameters (IGF-1 levels, comorbidities presence, tumor status, symptoms and health-related quality of life) that have been identified as the best predictors of disease activity and are divided into categories that indicate severity." (PMID 35322391, 2022). "Given the ability of GH and IGF1 to promote cell proliferation, cell movement and angiogenesis, and to suppress apoptosis, it is not surprising that dysregulation of the GH–IGF1 axis promotes neoplasia in human." (PMID 35966052, 2022). "Similarly, we also detected the PI3K activator IGF-1, although the tumor volume in the Cis+FJD-H+IGF-1 group mice was still higher than that in the model group, but it also hindered the tumor inhibitory effect of the Cis+FJD-H group as expected." (PMID 35281608, 2022). "We speculated that eIF2β promoted the synthesis and secretion of GH/IGF-1 in somatotroph tumor cells and inhibited immune cell infiltration." (PMID 36361871, 2022). "Whether tumor cells were pre-incubated with IGF-1 for 4 (DU145 cells) or 24 h (DU145, PC3 cells), a distinct increase in motile activity was noted, compared to unstimulated controls." (PMID 35053528, 2022). "Preclinical evidence has suggested that a high IGF1 environment in primary tumor stimulated tumor cells metastasis to bone, suggesting that bone metastases may reflect IGF dependency." (PMID 36193308, 2022). "Consequently, GH and IGF-1 levels were restored to normal range with remarkable tumor shrinkage after CAPTEM treatment." (PMID 35712496, 2022). "Therefore, in HCC, GH and IGF1 actions jointly create a highly proliferative and therapy resistant tumor phenotype." (PMID 35865483, 2022). "(a) Changes in metabolites in T2D patients, such as in insulin/IGF-1 and leptin/adiponectin secretion, may favor tumor development." (PMID 36553697, 2022). "IGF-1 plays a critical role in tumour development and progression." (PMID 36235868, 2022). "Similarly, strenuous exercise can increase the IGF1 levels and thus have deleterious effects by promoting the tumor growth." (PMID 36358820, 2022). "Those related factors change during tumor therapy which might also contribute to the heterogeneity of IGF-1 or IGFBP-3 levels." (PMID 36425849, 2022). "Importantly, IGF1 and Wnt/β-catenin signaling activation directly contributes to androgen-induced prostate oncogenesis and tumor development." (PMID 36323713, 2022).
tumor (continued). "Moreover, insulin increases the activity of insulin-like growth factor-1 involved in tumor initiation and progression." (PMID 35574372, 2022). "Serum levels of IGF-1 and insulin were also assessed at tumour endpoint." (PMID 35908046, 2022). "Similarly, dosage and time of administration of GH and IGF1 or their analogs for the repair of adjacent tissue damage after radiotherapy need to be determined according to the type of tumor cells for the most ideal effect." (PMID 34178997, 2021). "In cellular and animal models, GH and IGF‐1 promote tumour growth and progression." (PMID 33492754, 2021). "A recent report demonstrated that IGF-1–stimulated F-actin reorganization and cell motility occurs via the upregulation of RhoA protein expression and activity through the mTOR signaling pathway in tumor cells." (PMID 34627341, 2021). "In addition to the impact of circulating IGF1 on the hazard of developing a tumor, the expression and ligand-dependent activation (phosphorylation) of the IGF1R are regarded as key prerequisites for oncogenic transformation." (PMID 34204736, 2021). "Furthermore, several studies suggest that leptin and ObR are overexpressed in tumor tissues, due to hypoxia and/or as a response to insulin, IgF-1 and/or to estradiol." (PMID 33644151, 2021). "Our hypothesis is that the ability of SRL to reduce GH and IGF1 levels, shrink the tumor and soften tumor consistency depends on the doses of SRLs, so high doses of SRLs would be necessary for this purpose." (PMID 33289697, 2021). "Moreover, transgenic animals expressing the GH antagonist G120 GH had lower IGF-1 levels and exhibited decreased tumor incidence in the mammary gland relative to control mice after being treated with the carcinogen 7,12-dimethylbenz(a)anthracene (DMBA)." (PMID 34572814, 2021). "Moreover, the authors reported that MEG3 levels were positively correlated with GH and IGF1 serum levels, whilst they were negatively correlated with tumor size." (PMID 34484116, 2021). "Accordingly, mice bearing MCF-7 xenografts treated with pegvisomant, which is the clinical version of the G120R GH antagonist able to completely inhibit both GH and IGF-1 signaling in the mammary gland, displayed a 70–80% decreased of circulating IGF-1 and a 30% decrease in tumor size." (PMID 34572814, 2021). "Second, metformin can also reduce the activation of insulin/IGF-1 (insulin-like growth factor 1) receptors in tumor cells, resulting in reduced stimulation of the mitogenic pathway, thereby indirectly inhibiting cell proliferation, tumor formation and metastasis." (PMID 33976288, 2021). "A pivotal cause for the enhancement of ET anti-tumor activity by fasting or FMD appears to be the reduction in blood insulin, IGF1 and leptin, with the consequent inhibition of the PI3K–AKT–mTOR pathway, at least in part through the upregulation of EGR1 and PTEN." (PMID 34322508, 2021). "Tumor growth might be promoted by the direct action of insulin, as an anabolic factor and oncogene, or indirect action through IGF-1." (PMID 34208601, 2021). "Clinically and biochemically, they are similar to densely granulated somatotroph tumors, with florid features and elevated GH and IGF-1 levels, but they also have manifestations of prolactin excess, including amenorrhea and decreased libido, due to prolactin production by the tumor." (PMID 34067494, 2021). "These dietary approaches can reduce nutrient levels/factors that promote proliferation, particularly glucose, IGF1 and insulin, increase ketones body level which help to slow tumor growth and promote antitumor immunity and sensitization of cancer cells to the action of the immune system." (PMID 34322508, 2021).